RNU6-863P (RNA, U6 small nuclear 863, pseudogene)
Gene: Small nuclear RNA gene on chromosome 7 (76,087,444 to 76,087,547, forward strand). Ensembl gene ENSG00000251798.
Homologues: Orthologues: chimpanzee U6 (99% identical), macaque U6 (89% identical), pig U6 (80% identical), pig U6 (75% identical), dog U6 (74% identical). Paralogues in human: RNU6-912P (92% identical), RNU6-1254P (89% identical), RNU6-1319P (89% identical), RNU6-241P (89% identical), RNU6-747P (89% identical), RNU6-1052P (88% identical), RNU6-1076P (88% identical), RNU6-1100P (88% identical), RNU6-1118P (88% identical), RNU6-1199P (88% identical), RNU6-1217P (88% identical), RNU6-355P (88% identical), and 1287 more.